STAT3 (signal transducer and activator of transcription 3)
Diseases named in the same sentence as STAT3 in open-access papers (continued):
Sharing a sentence is not in itself a finding about the gene and the disease.
colon (18 papers, 2010 to 2025). "We and others have previously demonstrated that STAT3 signaling in response to IL-6 family cytokines provides a rate-limiting signal for gastrointestinal tumors that arise from bona fide oncogenic driver mutations, including in APC, KRAS, or other genes." (PMID 39128004, 2024). "In this study, we investigated the effect of a short deletion in the DNA-binding domain of STAT3 (STAT3del) on the transcriptional activation of STAT3 target genes and its relationship with colon carcinogenesis." (PMID 33535185, 2021). "Recently, leptin was shown to contribute to mucin production and the formation of gastrointestinal neoplasms by modulating mTOR-, STAT3-, and ERK-dependent pathways in addition to PKC-, PI3K-, and MAPK-dependent pathways." (PMID 26839577, 2016). "We performed a meta-analysis evaluating the prognostic role of p-STAT3 expression in patients with digestive system cancers." (PMID 26024373, 2015). "Expression of activated forms AKT, MEK, mTOR, p70 and STAT3 in the GI tumor cells used in this study each showed a significant partial protection of cells from [curcumin + sildenafil] induced cell death, abolishing the cell-death potentiating effect of sildenafil." (PMID 29245915, 2017). "Therefore we searched the available articles and performed the present meta-analysis in order to explore the prognostic value of p-STAT3 in patients with digestive system cancers." (PMID 26024373, 2015). "Phospho-STAT3 might be a prognostic factor of patients with digestive system cancers." (PMID 26024373, 2015). "Previous reports have demonstrated that FXR inhibits STAT3 phosphorylation by upregulating SOCS3 expression, thereby suppressing digestive system tumors." (PMID 39940889, 2025). "Considering that BFT induces inflammation, activates STAT3 and alters signalling pathways, it can be concluded that BFT produced by ETBF plays an important role in colon carcinogenesis." (PMID 32863742, 2020). "Additionally, studies have found that FXR inhibits the phosphorylation of STAT3 by upregulating the expression of SOCS3, thereby suppressing digestive system tumors." (PMID 39940889, 2025). "As the AOM/DSS model allows studying the sequential development of colon carcinogenesis, it could be interesting to compare the consequence of the inducible COL1-specific activation/inactivation of STAT3 at different time points during the AOM/DSS protocol in future studies." (PMID 35326623, 2022). "However, systemic Stat3 haploinsufficiency suppresses growth of gastrointestinal tumours, without interfering with physiological responses during adult, fecund life." (PMID 20478049, 2010).
heart disease (12 papers, 2012 to 2025). "Although there is huge progress in the function of STAT3 and miRNAs in cardiac disease and protection, the information on the crosstalk between STAT3 and miRNA is scarce." (PMID 36148063, 2022). "As a transcription factor, STAT3 upregulates anti-oxidative and anti-apoptotic genes but suppresses anti-inflammatory and anti-fibrotic genes in cardiac disease and protection." (PMID 36148063, 2022). "This review presents that STAT3 serves as the target of miRNAs and the upstream regulators of miRNAs that manage their transcriptional control in different cardiac diseases and protection." (PMID 36148063, 2022). "As a signaling molecule, STAT3 is the downstream or upstream of other molecules for signaling transduction, also activated in cardiac disease and protection." (PMID 36148063, 2022). "Signal transducer and activator of transcription 3 (STAT3), an important transcription factor and signaling molecule, play an important role in cardiac disease and protection." (PMID 36148063, 2022). "We summarize the current knowledge on STAT3 regulation of individual miRNAs and the modulation of STAT3 by miRNAs in cardiac diseases and protection." (PMID 36148063, 2022). "A remarkable amount of studies have shown the multifaceted roles of signal transducer and activator of transcription 3 (STAT3) and microRNAs (miRNAs) in cardiac disease and protection." (PMID 36148063, 2022). "A better understanding of the complex regulatory networks between STAT3 and miRNAs may lead to novel specific therapeutic approaches in various cardiac disease settings." (PMID 36148063, 2022). "Recently, STAT3 is reported to be not only the target of miRNA but also the inhibitor or inducer of miRNA to modify the mRNA expression profiles in cardiomyocytes resulting in different effects on cardiac diseases and protection." (PMID 36148063, 2022). "Recently, STAT3 is reported to be not only the target of miRNA but also the inhibitor or inducer of miRNA to modify the mRNA expression profiles in cardiomyocytes resulting in different effects on cardiac disease and protection." (PMID 36148063, 2022). "STAT3-miRNAs circuits in different cardiac diseases and protection." (PMID 36148063, 2022). "This beneficial effect of STAT3 may lead to the development of a novel therapeutic strategy for heart disease." (PMID 32178385, 2020). "Understanding the novel and often protective aspects of STAT3 in the myocardium could lead to new therapeutic approaches to treat heart disease." (PMID 30619368, 2018). "However, targeting STAT3 for the treatment of heart disease remains very challenging." (PMID 40561034, 2025). "In aggregate, our data indicate that there are molecular (STAT3 signaling), structural (lung MLI, bronchus-associated lymphoid tissue), and physiological differences (lung elastance, cardiac hypotonicity) in Dp16 mice that may predispose them to lung and heart disease." (PMID 37761959, 2023).
infectious disease (10 papers, 2013 to 2025). A disorder directly resulting from the presence and activity of a microbial, viral, or parasitic agent in humans. "The association of variants of the STAT3 gene with susceptibility to infectious diseases was also shown." (PMID 35327350, 2022). "Previous studies demonstrated that SOCS3-mediated IL-6/STAT3 signaling pathway regulates multiple cytokine signaling pathways in autoimmune and infectious diseases." (PMID 34147072, 2021). "Thus, these rare inborn errors of immunity, affecting ~1 in 100 000 live births, highlight the critical importance of balanced STAT3 signaling in human immunity to maintain homeostasis and prevent infectious disease, autoimmunity, and exaggerated inflammation." (PMID 39836489, 2025). "As a matter of fact, STAT3 is the most involved transducer activated by acute inflammatory stimuli that increase the transcription of IL-6, one of the main players in the acute phase response during inflammation and infectious diseases." (PMID 35408963, 2022). "This should be addressed in future studies which should also elucidate whether impaired regulatory IL-10 STAT3 signaling can be a marker of developing severe reactions to infectious diseases." (PMID 35039055, 2022). "In Cyld−/− mice, both increased NF-κB-dependent IL-6 production and K63-ubiquitination of STAT3 contribute to the enhanced STAT3 activity, which further illustrates the central importance of IL-6/gp130-dependent STAT3 activity for protective host responses in infectious diseases." (PMID 23825949, 2013). "In this context, we posit that the involvement of STAT3 activation in pathogenic mechanisms of autoimmune and infectious diseases may not be confined to CD4+ T cells." (PMID 24204098, 2013).
endocrinopathies (9 papers, 2019 to 2025). "Other genetic defects that lead to endocrinopathies include loss-of-function changes in IL2RA, STAT5B and GOF in STAT3 and STAT1." (PMID 40704637, 2025). "For endocrine system diseases such as DFU, signal transducer and activator of transcription 3 (STAT3) can promote fibroblast proliferation and migration to facilitate wound healing by activating the Chi3l1/MAPK axis, providing drug targets for the treatment of this disease." (PMID 39769202, 2024).
peripheral neuropathy (8 papers, 2014 to 2025). A disorder affecting the peripheral nervous system. "We also revealed that SH003 prevented docetaxel-induced peripheral neuropathy with inhibition of phospho-STAT3 at the sciatic nerves and spinal cords (L4 – L6), which is one of the readouts for chemotherapy-induced peripheral neuropathy." (PMID 38303001, 2024). "Pregabalin and lacosamide ameliorate paclitaxel-induced peripheral neuropathy via inhibition of JAK/STAT3 signaling pathway and Notch-1 receptor." (PMID 34857740, 2021). "Taken together, it is worth noting that TNF-α and IL-6 in plasma and phospho-NF-κB and phospho-STAT3 in spinal cord and sciatic nerves are putative biomarkers of docetaxel-induced peripheral neuropathy (DIPN) in mouse models." (PMID 34422067, 2021). "GPCR coupled signaling, including MAPKs, PI3K, STAT3 and NF-κB pathways, are proposed to function in CXCR4 signaling, and these pathways are also activated in the lumbar spinal cord following peripheral neuropathy." (PMID 25119456, 2014). "Peripheral neuropathy also activates STAT3 (restricted to spinal microglia) and AKT (restricted to spinal neuron); however our present study did not found any effect of intrathecal AMD3100 on STAT3 or AKT pathways." (PMID 25119456, 2014).
retinopathy (8 papers, 2016 to 2024). "Also, triggering JAK/STAT3 signals accentuate growth factor and cytokine-induced angiogenesis in oxygen-induced retinopathy." (PMID 39502139, 2024). "Using human retinal endothelial cells (HREC) exposed to hypoxia and a mouse model of oxygen-induced retinopathy (OIR), we found that TIMP3 expression was significantly decreased at both mRNA and protein levels and this paralleled the activation of STAT3 and up-regulation of miR-21." (PMID 29262585, 2017). "Moreover, the interaction between EP300 and STAT3 is increased by treatment with CNTF or FGF2, suggesting a possible mechanism whereby CNTF and FGF2 reduce apoptosis and protect photoreceptor cells from light-induced retinopathy." (PMID 27242532, 2016). "This study tested the hypothesis that endothelial cell-specific knockdown of VEGF receptor 2 (VEGFR2), or downstream STAT3, would inhibit VEGF-induced retinopathy without delaying physiologic retinal vascular development." (PMID 29730824, 2018).
vasculopathy (8 papers, 2020 to 2025). "Impaired tissue repair and angiogenesis, involving FGF1, FGF2, TGF-β, VEGF, and HIF-1α, has been implicated in vasculopathy and pseudoaneurysm formation in STAT3-HIES." (PMID 40491905, 2025). "Further research is needed to elucidate the mechanisms underlying vasculopathy in STAT3-HIES and establish optimal screening strategies to improve patient outcomes." (PMID 40491905, 2025). "This has implications for counseling and vascular surveillance, and highlights the need for further studies to determine the risk, pathogenesis, and optimal management of the vasculopathy associated with STAT3-HIES." (PMID 33014947, 2020). "An amplified JAK/STAT3 signaling in the endothelium caused severe vasculopathy, including a proinflammatory transcriptional profile leading to increased adhesivity and thrombogenicity of the endothelial surface, that was associated with a strong type I IFN–like response." (PMID 34138760, 2021). "Vasculopathy associated with STAT3-HIES may persist or arise following HSCT and can precipitate life-threatening complications." (PMID 33014947, 2020). "STAT3-HIES vasculopathy can involve any large or medium-sized artery, since the hepatic artery was also affected in this case." (PMID 40491905, 2025). "Patients with STAT3-HIES have been reported to develop vasculopathy involving the aortic, intracranial, coronary, and pulmonary arteries." (PMID 40491905, 2025). "Some patients with STAT3-HIES develop vasculopathy or pseudoaneurysms in the bronchial, coronary, or cerebral arteries due to endothelial fragility and impaired tissue repair." (PMID 40491905, 2025). "Vasculopathy in STAT3-HIES presents challenges to both understanding of pathogenesis and clinical management." (PMID 33932191, 2021). "We reviewed previous reports of vasculopathy in patients with STAT3-HIES including autosomal dominant or sporadic HIES without consanguinity." (PMID 40491905, 2025).
benign tumors (6 papers, 2009 to 2023). "Two of 25 benign tumors expressed mild cytoplasmic positivity for STAT3 whereas 6 intermediate tumors exhibited both mild and moderate cytoplasmic positivity for STAT3." (PMID 21575192, 2011).
connective tissue disease (6 papers, 2015 to 2023). "On the other hand, another report has shown that STAT3 deficiency causes skeletal and connective tissue disorders." (PMID 36386129, 2022). "We also find evidence for activation of multiple other inflammatory and connective tissue-disorder pathways mediated through pro-inflammatory TF genes such as STAT3, IRF1 and IRF7, CEBPB and SMAD4." (PMID 26202100, 2015).
intestinal disorder (6 papers, 2019 to 2024). A non-neoplastic or neoplastic disorder that affects the small or large intestine. "Several genome-wide studies on intestinal disorder patients identified variants of STAT3 as a risk factor for diseases development, and the activated expression of STAT3 in intestinal cells, including intestinal epithelial cells, was also detected in inflamed intestinal regions." (PMID 34337082, 2021). "Thus our studies identify a hepatocyte-specific Rela/Stat3 network as a potential therapeutic target for intestinal diseases." (PMID 39137024, 2024). "In intestinal disorders including IM, curcumin exerts its anti-inflammatory effects not only by inhibiting NF-κB activation but also contributes to its ability to regulate IL-6/STAT3 signaling." (PMID 34337082, 2021). "Therefore, IL-6/STAT3 signaling pathway is important for intestinal homeostasis maintenance, and regulation of this signaling is an approach in treatment of intestinal disorders." (PMID 34337082, 2021). "Indeed, IL-22, also known as a potent activator of STAT3, is also known as a regulator of intestinal homeostasis and is being developed as a drug for intestinal diseases such as IBD." (PMID 31277507, 2019). "Hence, we hypothesized that Shaoyao decoction can protect against intestinal ulcers by modulation Th17/Treg imbalance through the IL-6/STAT3 signaling pathway." (PMID 38001450, 2023). "Therefore, the pharmacological regulators of STAT3 maintaining STAT3 homeostasis and adequate STAT3 levels may be promising therapeutic candidates for intestinal disorders." (PMID 31277507, 2019).
genetic disorders (5 papers, 2020 to 2023). "In fact, mutations in STAT1 and STAT3 that dissociate latent dimers give rise to rare genetic disorders of the immune system." (PMID 37059181, 2023). "It was hypothesized that activated STAT3 maintains the symptoms of long COVID by altering immunity, a condition reminiscent of the rare genetic disorder STAT3 gain of function (GOF)." (PMID 37628830, 2023).
myopathy (5 papers, 2011 to 2022). A disease of the muscle in which the muscle fibers do not function properly. "Further studies will be needed to evaluate if STAT3 also plays a role in different inflammatory myopathies and if other patients with STAT3 mutations develop a muscle phenotype." (PMID 30072615, 2018). "PGC-1β upregulates apoptosis and/or autophagy-related TFs, such as Atf3 and Stat3, subsequently triggering myopathy." (PMID 35812340, 2022). "The studies presented here demonstrate that STAT3 can also play a role in myopathies." (PMID 30072615, 2018). "Concurrently, PGC1β up-regulates apoptosis and/or autophagy transcriptional factors such as E2f1, Atf3, Stat1, and Stat3, which may be facilitating myopathy." (PMID 28860475, 2017).
respiratory diseases (5 papers, 2020 to 2025). "Within the context of pulmonary cells, STAT3 is implicated in responding to environmental stressors and inflammatory signals prevalent in respiratory diseases." (PMID 40129771, 2025). "Several cellular mechanisms, including STAT3, are involved in the pathogenesis of PM-exacerbated respiratory diseases." (PMID 33374928, 2020). "Next, complementary analyses identified nine DMGs (LTA, STAT3, IKBKG, IRAK1, NOD2, TLR2, TNFRSF1A, and IKBKB) that might be involved in the immune response of XJB cattle infected with respiratory diseases." (PMID 38732144, 2024).
brain diseases (2 papers, 2019 to 2022). "The severity and progression of many brain diseases are also linked human neurovascular dysfunction, which suggested links between STAT3 activation in astrocytes and BBB dysfunction." (PMID 36323693, 2022). "Revealing the underlying mechanisms through which sEH orchestrates STAT3 activity and developing means to manipulate astrocytic sEH expression could facilitate the future development of treatment for brain diseases." (PMID 31176371, 2019). "The sEH-mediated STAT3 inhibition in a cellular context suggests that astrocytic sEH may play an important role in the regulatory machinery of pro-inflammatory response in activated astrocytes during the progression of the brain diseases." (PMID 31176371, 2019).
CNS neoplasms (2 papers, 2016 to 2024). "Potential targets for CNS tumors include Vascular Endothelial Growth Factor (VEGF), Bcl2, Stat3 and many immune related targets." (PMID 38348876, 2024).
biliary liver disease (1 paper, 2017). "Our data suggest that concurrent biliary liver disease provides a ‘second-hit’ which enforces HBsAg-associated carcinogenesis by the potentiated activation of proto-oncogene cJun and STAT3." (PMID 28881751, 2017).
central nervous system diseases (1 paper, 2025). "Furthermore, studies have shown that inhibiting the excessive activation of JAK2/STAT3 is an effective neuroprotective strategy in central nervous system diseases." (PMID 41208867, 2025).
musculoskeletal disorders (1 paper, 2025). "Notably, several studies suggest crosstalk between STAT3 and FoxO proteins in regulating oxidative stress and cell survival, pointing toward their convergence in age-related musculoskeletal disorders." (PMID 41282482, 2025).
nervous system tumors (1 paper, 2021). "However, a report showing that DMKN can affect the activation of STAT3 and down-stream molecular proteins of the MAPK and PI3K signaling pathways suggests that DMKN may play a role in nervous system tumors through this pathway." (PMID 33902636, 2021).
STAT3 also shares sentences with these, for which no sentence is quoted: Allergy (12 papers); hypertrophy (9); T-cell leukemia (8); acute myocardial infarction (7); viral diseases (7); skin abscesses (6); abscesses (5); airway hyperresponsiveness (5); somatotroph adenomas (5); tongue squamous cell carcinoma (5); X-linked agammaglobulinemia (5); alopecia areata (4); APECED syndrome (4); cerebral amyloid angiopathy (4); Crush Syndrome (4); endocervical adenocarcinoma (4); Felty syndrome (4); Glomerular sclerosis (4); muscle atrophy (4); neurotoxicity (4); Parkinson’s (4); spondyloarthritis (4); Ventricular hypertrophy (4); acute promyelocytic leukemia (3); adult T-cell leukemia (3); alcoholic cirrhosis (3); autoimmune enteropathy (3); autoimmune hemolytic anemia (3); bacterial pneumonia (3); bipolar disorder (3).
A further 329 diseases each share a sentence with STAT3 in 3 papers or fewer.